NRAL (NRF2 regulation associated lncRNA)
Gene: Long non-coding RNA gene on chromosome 2 (176,506,245 to 176,507,702, reverse strand). Ensembl gene ENSG00000229434.
Diseases named in the same sentence as NRAL in open-access papers:
NRAL is named in the same sentence as 2 diseases in open-access papers, as found by Europe PMC text mining. Sharing a sentence is not in itself a finding about the gene and the disease. The quoted sentences say what the papers report.
hepatocellular carcinoma (1 paper, 2020). A malignant tumor that arises from hepatocytes. "The dual and opposite roles of NRF2 regulation-associated lncRNA (NRAL) and KEAP1 regulation-associated lncRNA (KRAL) have been recently outlined in hepatocellular carcinoma (HCC) cell lines." (PMID 33287295, 2020).
cancer (1 paper, 2022). A tumor composed of atypical neoplastic, often pleomorphic cells that invade other tissues. "Recent studies show that various lncRNAs, such as HOTAIR, MALAT1, NRAL and TUG1, play a pivotal role in the regulation of cancer cells’ oxidative stress, highlighting a possible crossroad between lncRNAs and ROS." (PMID 36077530, 2022).